INS (insulin)
Description:
Insulin decreases blood glucose concentration. It increases cell permeability to monosaccharides, amino acids and fatty acids. It accelerates glycolysis, the pentose phosphate cycle, and glycogen synthesis in liver.
Synonyms: IDDM; IDDM1; IDDM2; ILPR; IRDN; MODY10; PNDM4
Tractability: Small molecule: a structure with a bound ligand is known. Antibody: its Gene Ontology location is reachable by antibodies, with high confidence; UniProt places it where antibodies can reach, with medium confidence; UniProt predicts a signal peptide or a membrane-spanning region.
Target class: Secreted protein
Gene: Protein-coding gene on chromosome 11 (2,159,779 to 2,161,221, reverse strand). Ensembl gene ENSG00000254647.
Subcellular location: Secreted
Pathways (Reactome):
Signal Transduction: IRS activation; Insulin receptor recycling; Insulin receptor signalling cascade; PI5P, PP2A and IER3 Regulate PI3K/AKT Signaling; Signal attenuation; Signaling by Insulin receptor
Metabolism of proteins: Amyloid fiber formation; Insulin processing; Synthesis, secretion, and deacylation of Ghrelin
Gene expression (Transcription): FOXO-mediated transcription of oxidative stress, metabolic and neuronal genes; NPAS4 regulates expression of target genes
Developmental Biology: Regulation of gene expression in beta cells
Metabolism: Regulation of insulin secretion
Vesicle-mediated transport: COPI-mediated anterograde transport
Gene Ontology:
Molecular function: hormone activity; identical protein binding; insulin receptor binding; insulin-like growth factor receptor binding; protease binding; protein binding; receptor ligand activity
Biological process: acute-phase response; alpha-beta T cell activation; fatty acid homeostasis; G protein-coupled receptor signaling pathway; glucose homeostasis; insulin receptor signaling pathway; negative regulation of acute inflammatory response; negative regulation of fatty acid metabolic process; negative regulation of feeding behavior; negative regulation of gene expression; negative regulation of glycogen catabolic process; negative regulation of lipid catabolic process; negative regulation of protein catabolic process; negative regulation of protein secretion; negative regulation of reactive oxygen species biosynthetic process; negative regulation of respiratory burst involved in inflammatory response; neuron projection maintenance; nitric oxide-cGMP-mediated signaling; positive regulation of canonical NF-kappaB signal transduction; positive regulation of cell population proliferation; positive regulation of cytokine production; positive regulation of D-glucose import; positive regulation of dendritic spine maintenance; positive regulation of gene expression; positive regulation of glycogen biosynthetic process; and 30 more
Cellular component: extracellular region; endoplasmic reticulum lumen; endoplasmic reticulum-Golgi intermediate compartment membrane; endosome lumen; Golgi lumen; Golgi membrane; secretory granule lumen; transport vesicle
Genetic constraint (gnomAD): Loss-of-function variants: 7 observed, 11 expected, observed/expected ratio (o/e) 0.64, 90% interval 0.36 to 1.2. The upper end of that interval is the gene's LOEUF score, 1.2, which puts it in group 5 of 6, group 1 being the genes least tolerant of losing a copy. Missense variants: 109 observed, 136.51 expected, observed/expected ratio (o/e) 0.8, 90% interval 0.68 to 0.94. Synonymous variants: 71 observed, 62.98 expected, observed/expected ratio (o/e) 1.13, 90% interval 0.93 to 1.37.
Gene-disease validity (ClinGen):
ClinGen rates the evidence that INS causes each of these diseases.
monogenic diabetes (autosomal dominant; autosomal recessive): Definitive. Diabetes mellitus that is caused by mutations in a single gene.
Homologues: Orthologues: macaque INS (98% identical), dog INS (88% identical), pig INS (85% identical), rabbit INS (85% identical), rat Ins1 (83% identical), rat Ins2 (83% identical), mouse Ins2 (82% identical), mouse Ins1 (78% identical), guinea pig INS (69% identical), chimpanzee INS (59% identical), tropical clawed frog ins (56% identical), zebrafish ins (45% identical), and 1 more. Paralogues in human: IGF2 (32% identical), IGF1 (31% identical).
Diseases named in the same sentence as INS in open-access papers:
INS is named in the same sentence as 1,597 diseases in open-access papers, as found by Europe PMC text mining. Sharing a sentence is not in itself a finding about the gene and the disease. The quoted sentences say what the papers report.
diabetes (28,905 papers, 1923 to 2026). "Previous studies have consistently shown that longer diabetes duration is associated with poorer glycemic control, largely due to progressive beta-cell dysfunction and reduced insulin secretory capacity." (PMID 41601869, 2026). "Diabetes represents a chronic metabolic disease, characterised by either an absolute loss of the production of insulin (Type I Diabetes—insulin-dependent diabetes) or a decrease in sensitivity to insulin (Type II diabetes—non-insulin-dependent diabetes)." (PMID 41590669, 2026). "Endocrine therapies, like tamoxifen, aromatase inhibitors, and GnRH agonists, increase diabetes risk potentially by reducing insulin sensitivity and promoting apoptosis in pancreatic β‐cells." (PMID 41287203, 2026). "Type 1 diabetes mellitus (T1D) is characterized by the autoimmune destruction of pancreatic beta cells, leading to insulin deficiency and necessitating lifelong external insulin administration." (PMID 41797233, 2026). "Accumulating evidence implicates both central and peripheral 5-HT signaling in the regulation of insulin signaling and glucose homeostasis, with dysregulations of 5-HT levels being associated with impaired insulin function and diabetes development." (PMID 41424854, 2026). "This study sought to evaluate the association between insulin‐related mechanisms underlying diabetes, which differ by sex in conjunction with distinct glucose profiles." (PMID 41133433, 2026). "It assesses general and diabetes-specific disordered eating behaviors including weight loss, dietary restriction, insulin omission, and vomiting." (PMID 41484931, 2026). "Diabetes mellitus is a global metabolic disorder characterized by chronic hyperglycemia, primarily arising from insulin secretion deficiency due to pancreatic β-cell dysfunction and insulin resistance in peripheral tissues." (PMID 41601937, 2026). "GLP-1RAs and DPP-4is have gained prominence in diabetes therapy due to their ability to enhance insulin secretion, promote weight loss, and reduce cardiovascular risk." (PMID 41189469, 2026). "In conclusion, insulin therapy restored the diabetes-induced loss of renal NEP protein and decreased the diabetes-induced rise in renal Arg-2 protein, suggesting a reversal of critical molecular changes in the diabetic kidney." (PMID 41601953, 2026). "Diabetes mellitus is a major chronic metabolic disease characterized by persistent hyperglycemia resulting from impaired insulin secretion, impaired insulin action, or both, and is associated with microvascular and macrovascular complications." (PMID 42220722, 2026). "This study aimed to determine the prevalence and clinical characteristics of EPI in patients with type 1 (T1DM) and type 2 diabetes mellitus (T2DM) and to evaluate its associations with diabetes-related complications and insulin therapy." (PMID 42279180, 2026). "Multivariable linear regression analyses assessed relationships between LAN and diabetes risk markers, including hemoglobin A1c (HbA1c), fasting blood glucose, fasting serum insulin, and Homeostasis Model Assessment of Insulin Resistance (HOMA-IR)." (PMID 42175485, 2026). "Diabetes mellitus (DM) has been regarded as a chronic metabolic disorder featuring a deficiency in insulin secretion and action." (PMID 41487898, 2026). "The diagnostic criteria based on the DSM-5-TR, have been revised to include insulin omission, a unique ‘purging’ behavior employed by those with diabetes for weight loss (partially through inducing a catabolic state)." (PMID 41484931, 2026). "While ion channel defects disrupt the real-time function of insulin secretion, mutations in transcription factors cause diabetes by impairing the embryological development of the pancreas and β-cell differentiation." (PMID 41614934, 2026). "Diabetes mellitus (DM) is a chronic metabolic disease caused by abnormal insulin levels in the body." (PMID 41541001, 2026).
diabetes (continued). "Because normal calcium homeostasis and mitochondrial function are crucial for insulin secretion, this variant likely impairs insulin release, leading to diabetes." (PMID 41498801, 2026). "Alterations in Ca2+ coordination among beta-cells contribute to defective insulin secretion, which underlies all forms of diabetes mellitus." (PMID 42064760, 2026). "Diabetes mellitus is primarily caused by the loss or malfunction of insulin-producing β-cells, and although current therapies improve glycemic control, they do not restore physiologic insulin secretion." (PMID 42072272, 2026). "Such microgranules have been reported in other diabetes models, where they are associated with diminished β cell insulin content." (PMID 41252202, 2026). "Mechanistically, the nuclear receptor PPARγ, previously linked to Metrnl’s insulin-sensitizing effects in diabetes, appears central to this switch." (PMID 41493486, 2026). "There are many INS gene variants generating a range of clinical phenotypes from permanent neonatal diabetes to clinically silent." (PMID 41516356, 2026). "Among the various fat distributions in the human body, abdominal obesity contributes to the development of diabetes mellitus because excess abdominal fat can cause insulin resistance, inflammation and glucose metabolism dysregulation." (PMID 41499450, 2026). "Dysregulation of insulin signaling has been implicated in several diseases, including diabetes mellitus, metabolic syndrome, certain cancers, and neurodegenerative diseases, such as Alzheimer's disease." (PMID 41683647, 2026). "Obesity and type 2 diabetes mellitus are closely linked metabolic disorders in which gut microbial alterations interact with host epigenetic regulation to influence inflammation, insulin sensitivity, and energy homeostasis." (PMID 41988036, 2026). "In an earlier study, we discovered six different prediabetes clusters, Tübingen Diabetes Risk Clusters, by analysing data of anthropometric measurements, MRI and biomarkers of insulin sensitivity, secretion and glycemia of about 900 people." (PMID 41547928, 2026). "Biallelic loss-of-function ZNF808 variants were recently identified as a cause of pancreatic agenesis characterised by insulin-treated permanent neonatal diabetes (PNDM), low birthweight and exocrine pancreatic insufficiency." (PMID 41500078, 2026). "Exposure to endocrine-disrupting chemicals (EDCs) is increasingly recognized as a risk factor for diabetes, primarily through disruption of pancreatic beta-cell function and insulin signaling." (PMID 41264466, 2026). "Precision nutrition has emerged as a promising strategy for the prevention of type 2 diabetes mellitus (T2DM) by targeting molecular pathways underlying insulin resistance and impaired glucose metabolism." (PMID 41751766, 2026). "Before the introduction of detailed perioperative insulin regimens, surgery on people with diabetes carried a mortality risk of 3.7–13.2%." (PMID 40480914, 2025). "This cohort study compares the risk of glycemic outcomes and adverse events among insulin-treated adults with diabetes and Alzheimer disease and related dementias who use either continuous glucose monitoring (CGM) or self-monitoring of blood glucose." (PMID 41329488, 2025). "Diabetes mellitus (DM) is one of the most common chronic endocrine diseases, the pathogenesis of which is due to metabolic disorders caused by abnormal insulin secretion, with clinical manifestations of chronic hyperglycemia." (PMID 41262264, 2025). "Type 1 diabetes mellitus arises due to autoimmunity targeting the insulin-producing beta cells, leading to insulin deficiency." (PMID 40260359, 2025). "Diabetes mellitus is a chronic metabolic disorder characterized by elevated blood glucose levels, which arise from deficiencies in insulin secretion, insulin action, or a combination of both." (PMID 40572453, 2025).
diabetes (continued). "Here, we show that despite VH125SD BCR transgene-forced expansion of anti-insulin B cells, T cell loss of Bcl6 led to nearly complete prevention of diabetes in VH125SD mice." (PMID 40909612, 2025). "Diabetes mellitus is characterized by the loss of pancreatic insulin-secreting β-cells in the Islets of Langerhans." (PMID 40236756, 2025). "This reduction likely reflects advancements in the management of diabetes, including the widespread use of insulin pumps and improved prophylaxis and diagnostic strategies for PE." (PMID 40521220, 2025). "Disruptions in this finely tuned network underlie the pathogenesis of diabetes, where imbalances in hormone secretion led to hyperglycemia, impaired insulin action, and dysregulated counterregulatory responses." (PMID 40919135, 2025). "Lower liver density is significantly associated with diabetes status and higher HbA1c, whereas lower skeletal muscle density is associated with higher glucose and insulin levels." (PMID 40533477, 2025). "Sodium-glucose cotransporter-2 inhibitors are not recommended for T3cDM until their safety is confirmed with regard to the risk of euglycemic diabetic ketoacidosis in insulin-deficient states." (PMID 40401174, 2025). "This destruction leads to the loss of insulin-producing cells, which is more severe and rapid compared to classical type 1 diabetes mellitus (T1DM)." (PMID 39859105, 2025). "Some studies have indicated that the glycemic load (GL) is an important determinant of an increased risk of diabetes and insulin release." (PMID 40002091, 2025). "LADA is defined as diabetes that develops in people aged 30 years or older, who have at least one islet cell-associated autoantibody, and who are insulin-independent for at least 6 months after diagnosis." (PMID 40226121, 2025). "Blautia is associated with diabetes, obesity, the inhibition of insulin signaling, and inflammatory diseases." (PMID 41179493, 2025). "The more recent advancements in HCL technology have allowed for automated insulin delivery based on glucose trends, resulting in improved overall diabetes control, reduced risk of hypoglycemia, and decreased disease burden." (PMID 39933614, 2025). "In kidney stone patients, normal insulin sensitivity can prevent blood glucose metabolism disorders, reduce the risk of metabolic diseases such as diabetes, and exert a positive impact on all-cause mortality." (PMID 40612299, 2025). "Several retrospective studies have reported associations between declining insulin needs and adverse outcomes in women with pre-existing diabetes." (PMID 41227133, 2025). "Patients with KCNJ11 and ABCC8 mutations typically present with isolated diabetes, and many can transition from insulin therapy to oral sulfonylureas, providing an effective alternative treatment strategy." (PMID 40443916, 2025). "LacCer 14:0, 16:0 and 24:1 were linked to reduced diabetes risk, perhaps due to anti-inflammatory or insulin-sensitizing effects." (PMID 40980166, 2025). "The most commonly associated factors included longer diabetes duration, older age, higher BMI (overweight/obesity), female gender and various diabetes treatment modalities (OADs/OADs and insulin/insulin only)." (PMID 41395632, 2025). "Aminoadipic acid, a lysine product associated with diabetes and known to be an insulin secretagogue, was lower in the heart of the experimental diets, especially the HFD group." (PMID 40463962, 2025). "Type 2 diabetes mellitus (T2DM) is a metabolic disorder characterized by increased blood glucose concentrations due to insulin resistance and a relative deficiency in insulin production." (PMID 39861423, 2025). "A meta-analysis of 107 trials found that HRT reduced fasting glucose by 2.5% (95% CI: (1.5, 3.5)) and fasting insulin by 9.3% (95% CI: (4.9–13.7)) resulting in an estimated 30% reduction in the risk of developing diabetes." (PMID 41334715, 2025).
diabetes (continued). "On the other hand, T2D is characterized by a combination of insulin and a relative deficiency of insulin production, making up 90 to 95% of all diabetes cases." (PMID 40559766, 2025). "Even so, the mechanism of diabetes associated with ciliopathies is not fully understood; it is suggested ciliary dysfunction is implicated in insulin signaling and secretion in the beta cells, resulting in type 2 diabetes." (PMID 40710848, 2025). "Diabetes mellitus (DM) is a clinical condition characterized by a deficiency in the action/secretion of insulin, leading to abnormal alterations in blood glucose levels." (PMID 39950195, 2025). "In our cohort, only the patients with insulin-treated gestational diabetes showed indications for a genetic predisposition, as there were more cases with a family history of diabetes mellitus." (PMID 39384641, 2025). "Among the genetic causes, monogenic forms of diabetes (MFD) refer to diabetes resulting from single-gene defects that affect insulin production or secretion." (PMID 41614819, 2025). "Teplizumab works by slowing the autoimmune destruction of β-cells, helping to prolong insulin production and reduce the need for exogenous insulin, which can improve glycemic control and lower the risk of long-term diabetes complications." (PMID 40333284, 2025). "Quantitative studies have employed AI to optimize insulin management, predict long-term diabetes risk, and model sustainable food systems." (PMID 41154976, 2025). "Poor glycemic control was prevalent and significantly associated with combined insulin and oral therapy, inadequate patient understanding of pharmacist instructions, and poor diabetes self-care practices." (PMID 40385776, 2025). "Collectively, these results indicate that LB-A has potential therapeutic effects by enhancing insulin levels and alleviating symptoms associated with diabetes mellitus in affected murine models." (PMID 41373699, 2025). "Type 2 diabetes mellitus (T2DM) is a prevalent metabolic disorder caused by impaired insulin secretion from pancreatic β-cells and insulin resistance in target tissues." (PMID 40362254, 2025). "Diabetes is a chronic disease caused by an inherited or acquired deficiency in insulin production by the pancreas or the body’s inability to use the insulin it produces adequately." (PMID 40308637, 2025). "The etiology of diabetes is mainly attributed to the combination of genetic and environmental factors, mainly due to insulin deficiency or insufficient insulin secretion, leading to glucose, lipid, and protein metabolism disorder." (PMID 40076321, 2025). "Causally, diminished beta cell function and insulin action in offspring of patients with T2D have been proposed to explain increased diabetes risk." (PMID 40531860, 2025). "Diabetes mellitus (DM) is a chronic metabolic disease caused by defects in the pancreatic islets and/or insulin function." (PMID 41347135, 2025). "Type 3c diabetes mellitus is a secondary form of diabetes associated with pancreatic disease, primarily chronic pancreatitis, which impairs insulin and glucagon secretion, resulting in inadequate glycemic control." (PMID 40401174, 2025). "Current research suggests that mature pancreatic β-cells can dedifferentiate into endocrine progenitor cells, leading to the loss of β-cell function, reduced insulin secretion, and the progression of diabetes." (PMID 40365319, 2025). "Current therapeutic interventions for DbCM primarily target individuals with underlying diabetes via the use of the antidiabetic drugs, metformin and insulin." (PMID 41214779, 2025). "The accumulation of iron ions in the body leads to oxidative stress and abnormal insulin synthesis and release, thereby increasing the risk of diabetes." (PMID 40471290, 2025).